UBE2WP1 (ubiquitin conjugating enzyme E2 W pseudogene 1)
Synonyms: UBE2WP
Gene: Processed pseudogene on chromosome 1 (96,418,594 to 96,418,933, forward strand). Ensembl gene ENSG00000234422.
Diseases named in the same sentence as UBE2WP1 in open-access papers:
UBE2WP1 is named in the same sentence as 1 disease in open-access papers, as found by Europe PMC text mining. Sharing a sentence is not in itself a finding about the gene and the disease.
UBE2WP1 shares sentences with these, for which no sentence is quoted: diabetes (1 paper).